GABRG2 (gamma-aminobutyric acid type A receptor subunit gamma2)
Diseases named in the same sentence as GABRG2 in open-access papers (continued):
Sharing a sentence is not in itself a finding about the gene and the disease.
epilepsy (continued). "The precise mechanism of GABRG2-related epilepsy is complex and requires further study in the future." (PMID 35359574, 2022). "The phenotypic spectrum and prognosis of patients with GABRG2-related epilepsy were further studied." (PMID 35359574, 2022). "Phenotypes of GABRG2-related epilepsy were ranged from mild febrile seizures to severe epileptic encephalopathies." (PMID 35359574, 2022). "The currently known epilepsy-associated variants identified in GABAA receptor subunits are predominantly distributed in the four genes (GABRA1, GABRB2, GABRB3 and GABRG2) that code for the most commonly distributed receptor isoforms." (PMID 34095830, 2021). "In a Gabrg2+/Q390X knockin mouse model of epilepsy, we identified mutant protein accumulation in newborn mouse pups, but the mutant protein aggregates did not emerge until later in life." (PMID 34281185, 2021). "Looking into the DEG subnetwork, we found that some well-known ASD candidate genes, such as Kcnma1, Shank2, Cacna1a and Cacna1b, and epilepsy candidate genes, such as Scn3a, Grin2a, Gabrg2, and Grin2b, are hub genes in this subnetwork." (PMID 32033586, 2020). "In fact, case reports identify photosensitivity as a potential phenotypic feature of GABRG2-related epilepsy in humans." (PMID 31582559, 2019). "In fact, in human patients on the severe end of the phenotypic spectrum of GABRG2-related epilepsies, seizures start very early in life." (PMID 31582559, 2019). "Taken together, these results show that CHRM3 is strongly co-expressed with GABRG2, HRH3, and CHRNA4 (risk genes for psychotic disorders, epilepsy, and schizophrenia) in THAL and other brain tissues." (PMID 31740666, 2019). "Five genes, ABCB1, ABCB4, CHRNA7, GABRA1, and GABRG2, are located within reported CNV regions and have been studied previously for their association with epilepsy as collected by HuGE." (PMID 21390307, 2011). "The observation of GABRA1 and GABRG2 in our network provides strong evidence of the association between GABAA receptors and epilepsy." (PMID 21390307, 2011). "Our model adds to the growing list of other specific human epilepsy knockin mice, including the Gabrg2, Kcnq2, Kcnq3, Scn1a and Chrna4 mice, to report a clear-cut genotype to phenotype seizure susceptibility." (PMID 19763161, 2009). "Notably, a lead derivative downregulated Gabrg2, a GABA-A receptor subunit implicated in epilepsy and other disorders of inhibitory synapses, highlighting a potential link between skeletal muscle signaling and neuropsychiatric disease." (PMID 42282775, 2026). "As CZP and LTG are both voltage‐gated sodium channel blockers, the ineffectiveness of CZP and LTG in animal models and patients indicated that sodium channels were not significantly affected in the epilepsy induced by GABRG2 mutations." (PMID 38357846, 2024). "Some studies have shown that the GABRG2 gene may be correlated with both epilepsy and drug-resistant epilepsy and so we conducted some meta-analyses of GABRG2 rs211037." (PMID 37275237, 2023). "Several monogenic epilepsies may result from mutations in the GABRA1, GABRB3, and GABRG2 genes encoding for the predominant α1β3γ2 GABAA isoforms." (PMID 38003469, 2023). "To date, systematic research on the phenotypic spectrum and prognosis of GABRG2 variants related to epilepsy is lacking." (PMID 35359574, 2022). "After searching in DrugBank, we retrieved a total of 47 anti-epileptic drugs and 151 targets, of which identified 17 target genes (CACNA1A, CHRNA4,CHRNA7,GABRA1,GABRA2,GABRB2,GABRG2,GRIK1,GRIN1,GRIN2B,KCNQ2,KCNQ3,SCN1A,SCN2A, SCN3A,SCN8A and SCN9A) were overlapped with risk genes of epilepsy." (PMID 36006933, 2022). "Several studies have documented the phenotypic heterogeneity of GABRG2-related epilepsy." (PMID 35359574, 2022). "In the literature, the phenotypes of some patients with epilepsy carrying GABRG2 variants were not described in detail; therefore, we were only able to analyze the genotype and phenotype correlations in our cohort." (PMID 35359574, 2022).
epilepsy (continued). "In our studies on GABRG2 loss-of-function epilepsy mutations with or without ER stress, a correlation of epilepsy phenotype severity with ER stress has been identified." (PMID 34281185, 2021). "Mutations in the GABRG2 gene encoding the γ-aminobutyric acid (GABA) A receptor gamma 2 subunit are associated with genetic epilepsy with febrile seizures plus, febrile seizures plus, febrile seizures, and other symptoms of epilepsy." (PMID 34050134, 2021). "In Gabrg2+/Q390X epilepsy mouse models, the existence of the mutant protein that is aggregation prone with slow degradation promotes a mild infrequent absence to a much severe epilepsy phenotype of DS with increased seizure severity and cognitive impairment." (PMID 34281185, 2021). "However, potassium voltage-gated channel subfamily Q member 2 (KCNQ2), SCN1A, and GABRG2 are three established genes among top ten genes for common epilepsies." (PMID 33096746, 2020). "Regarding the putative clinical associations for these polymorphisms, the GABRG2 SNP designated as rs211035 was previously investigated in relation to epilepsy with negative results." (PMID 29445327, 2018). "We found that variants in the epilepsy-associated genes GABRA1, GABRB3 and GABRG2 were mainly present in the ESP variants, but the GEC cohort contained epilepsy-associated GABRA6, GABRB1, and GABRB2 and non-epilepsy- associated GABRA4, GABRA5, and GABRG3 genes." (PMID 27622563, 2016). "Functionally significant association of drug target genes such as GABRG2 and SCN1A and efflux transporter gene ABCB1 to susceptibility to epilepsy in the present population needs to be seen in combination rather than isolation in evaluating therapeutic response." (PMID 24586633, 2014). "Furthermore, in one patient with atypical Rett syndrome, we found a pathogenic mosaic variant in the GABRG2 gene, which is usually associated with different epilepsy phenotypes but has not been reported elsewhere in association with Rett syndrome." (PMID 38279250, 2024). "Thus, in this study, we aimed to discuss the possible connections between SLC6A11, GABRG2, and targeted genetic variation in DRE to provide novel targets and strategies for the treatment of epilepsy in the future." (PMID 37275237, 2023). "This study found that across all three classes of epilepsy like severe developmental and epileptic encephalopathies, GGE and non-acquired focal epilepsy, gene GABRG2 were enriched for missense variants." (PMID 33096746, 2020). "However, targeted gene panel sequencing for SCN1A, SCN2A, and GABRG2, which are associated with GEFS+, showed no pathogenic mutations in the 11 children subsequently diagnosed with epilepsy in this study." (PMID 33212914, 2020). "In an earlier study on the same population we reported that a synonymous variant in GABRG2 rs211037 and SCN1A rs3812718 may have a putative role in increasing the risk of epilepsy, which was independent of its phenotype, that is, MTLE-HS or Juvenile myoclonic epilepsy." (PMID 24586633, 2014). "Several other genes that we have identified as undergoing mTLE-linked alternative splicing events also have been associated with other, non-mTLE forms of human epilepsy, including CACNA1A, CACNA1H, CLCN2, and GABRG2, indicating that these also may be of particular interest in the epilepsy field." (PMID 17343748, 2007).
Dravet syndrome (22 papers, 2012 to 2025). "A number of mutations have been identified in the γ2 subunit-encoding gene GABRG2, and these mutations are associated with a range of neurological phenotypes, from anxiety and childhood absence epilepsy on one end to Dravet syndrome on the other end." (PMID 38731820, 2024). "Many genetic epilepsies are associated with misfolded mutant proteins, including GABRG2(Q390X)-associated Dravet syndrome, which we have previously shown to result in intracellular accumulation of mutant GABAA receptor γ2(Q390X) subunit protein." (PMID 38731820, 2024). "All together this study suggests a novel mechanism of SWO-triggered seizures in het Gabrg2+/Q390X KI mice for one genetic generalized epilepsy such as Dravet syndrome due to Gabrg2Q390X mutation." (PMID 36632186, 2023). "Mutations in GABRs, especially in GABRA1, GABRB2, GABRB3, and GABRG2, impair GABAergic signaling and are frequently associated with DEEs such as Dravet syndrome and Lennox–Gastaut syndrome, as GABAergic signaling is critical for early brain development." (PMID 36077081, 2022). "A Dravet syndrome-associated mutation, GABRG2(Q390X), results in intracellular accumulation of misfolded protein." (PMID 35327449, 2022). "Using targeted next-generation sequencing, we identified a novel de novo GABRG2 missense mutation, P302L, in a patient with Dravet syndrome." (PMID 28197552, 2017). "Additionally, GABRG2 variants have been observed in individuals affected by Dravet syndrome, autism spectrum disorder, developmental delay and intellectual disability." (PMID 35274098, 2022). "Using the advantage of next-generation sequencing (NGS) technologies, we discovered nine novel de novo variants in GABRA1, GABRB2 and GABRG2 that were associated with Dravet syndrome and code for subunits that form the most common GABAA receptor (the α1β2γ2 receptor)." (PMID 34095830, 2021). "There are variants in GABRA1, GABRB2 or GABRG2 that are all associated with Dravet syndrome." (PMID 34095830, 2021). "Thus, based on our promising in vitro results showing that ZNS normalizes GABAAR expression, we speculated that ZNS would help reduce seizures in Dravet syndrome caused by the GABRG2(Q390X) mutation." (PMID 38731820, 2024). "Thus, ZNS may be useful for GABRG2(Q390X)-associated Dravet syndrome." (PMID 38731820, 2024). "In general, variants in the GABRG2 result in a broad spectrum of phenotypic severity, ranging from asymptomatic, FS, genetic epilepsy with febrile seizures plus (GEFS+), and Dravet syndrome individuals." (PMID 36979350, 2023). "In summary, we have reported a case of DEE associated with a deletion in GABRG2, which has been previously associated with febrile seizures, CAE, GEFS+, and Dravet syndrome." (PMID 36077081, 2022). "In this study, we identified nine patients with Dravet syndrome caused by variants in three relevant, but different, genes, GABRA1, GABRB2 or GABRG2." (PMID 34095830, 2021). "Next-generation sequencing on 870 patients with Dravet syndrome identified nine variants in GABRA1, GABRB2 and GABRG2 genes, which encode the most common α1β2γ2 GABAA receptor in the CNS." (PMID 34095830, 2021). "Heterozygous nonsense mutations in the γ-aminobutyric acid type A (GABAA) receptor γ2 subunit gene, GABRG2, and missense mutations in the GABAA receptor α1 subunit gene, GABRA1, are associated also with Dravet syndrome." (PMID 28197552, 2017). "We identified a de novo missense mutation, P302L, in the γ-aminobutyric acid type A (GABAA) receptor γ2 subunit gene GABRG2 in a patient with Dravet syndrome using targeted next-generation sequencing." (PMID 28197552, 2017). "Recently, GABAA receptor subunit genes (GABRs) encoding α1 (GABRA1), β3 (GABRB3) and γ2 (GABRG2), but not β2 (GABRB2) or β1 (GABRB1), subunits are frequently associated with Dravet syndrome or Dravet syndrome-like phenotype." (PMID 34095830, 2021).
Dravet syndrome (continued). "In addition, in female het Gabrg2+/Q390X KI mice, EEG delta-frequency (0.1–4 Hz) power during NREM sleep was significantly larger than that in male het Gabrg2+/Q390X KI mice, which likely contributes to gender difference in seizure incidence in human Dravet syndrome patients." (PMID 36632186, 2023).
generalized epilepsy (10 papers, 2021 to 2025). Epilepsy that is characterized by generalized seizure types and may have typical interictal and/or ictal EEG findings that accompany generalized seizure types (for example generalized spike-wave). "Recently, a study on associating ultra-rare coding variants with genetic generalized epilepsy through a case-control whole-exome sequencing study demonstrated that ultra-rare coding variants (URVs) in GABRG2 is an underlying important risk factor for GGE." (PMID 40217359, 2023). "Previous studies have shown that mutations of the GABA receptors, such as, GABRA1, GABRA5, GABRA6, GABRB3, GABRD, GABRG2, were associated with idiopathic generalized epilepsy." (PMID 35663265, 2022). "The GABRG2 gene polymorphisms C588T and 3145G>A could be predictive genetic markers that trigger idiopathic generalized epilepsy (IGE) or predict pharmaco-resistance to antiseizure medications (ASMs)." (PMID 41146305, 2025). "Mutations in genes encoding GABAA receptor subunits, such as GABRA1, GABRB3, GABRG2, and GABRD, have been identified in patients with idiopathic generalized epilepsies, Dravet syndrome, childhood absence epilepsy, and febrile seizures." (PMID 41614796, 2025). "A pro83-to-ser (P83S) substitution in GABRG2 was identified in a French Canadian family with idiopathic generalized epilepsy." (PMID 40217359, 2023). "When compared to the GABRG2- (rs211037-) CC genotype, the odds ratio for developing idiopathic generalized epilepsies in people with the GABRG2- (rs211037-) TT genotype was 4.2 (95%CI = 1.7 − 10.2)." (PMID 36425336, 2022). "In individuals with idiopathic generalized epilepsies, the GABRG2- (rs211037-) TT genotype was overrepresented relative to healthy control participants (IGE = 26.13 percent vs. control = 10.71 percent, P = 0.008)." (PMID 36425336, 2022). "There are also variants in GABRA1, GABRB3 or GABRG2 that are all associated with GGEs ranging from CAE, generalized epilepsy with febrile seizures plus (GEFS+), myoclonic atonic epilepsy (MAE) to other developmental EEs." (PMID 34095830, 2021). "Individuals having mutated GABRG2 are prone to febrile seizures, childhood absent epilepsy, and generalized epilepsy with febrile seizures plus." (PMID 36425336, 2022). "This study suggested that the GABRG2 C588T polymorphism might pose a risk for idiopathic generalized epilepsy but not for ADR in Pakistani population." (PMID 36425336, 2022). "When compared to the GABRG2- (rs211037-) CC genotype, the odds ratio for developing idiopathic generalized epilepsies among those with the GABRG2- (SNP211037-) TT and GABRG2- (rs211037-) CT genotype was 1.7." (PMID 36425336, 2022).
juvenile myoclonic epilepsy (8 papers, 2012 to 2025). "Missense or nonsense mutations of GABRA1, GABRB3, and GABRG2 are linked with GEFS+, childhood absence epilepsy, febrile seizures, and juvenile myoclonic epilepsy." (PMID 38003469, 2023). "In contrast, Balan and colleagues agreed with the initial finding of an association between the GABRG2 C588T C allele and the CC genotype with mesial temporal lobe epilepsy and juvenile myoclonic epilepsy but could not find a real effect of different genotypes on the efficacy of ASMs." (PMID 41146305, 2025).
depression (7 papers, 2016 to 2023). "GABRG2 was found to be associated with suicidal behavior and major depressive disorder." (PMID 36970514, 2023). "CIS-induced decreases in DRD1 and GABRG2 levels might be involved in the increase in susceptibility to depression in this context." (PMID 33863350, 2021). "Thus, CIS-induced decreases in DRD1 and GABRG2 levels might be involved in susceptibility to depression in middle-aged female mice." (PMID 33863350, 2021). "Specifically, one study found that the subunit of GABAA receptors, GABRG2, had a higher gene expression in the dorsolateral prefrontal cortex of individuals with major depression, while another study found lower GABRG2 brain expression in suicide behavior individuals who died by suicide." (PMID 37371384, 2023). "This study may provide new evidence for cognitive deficit of suicide and depression, and find the relationship between GABRG2 and cognitive deficit." (PMID 34733184, 2021). "However, how DRD1 and the levels of the GABAA receptors GABRA1, GABRB2 and GABRG2 change in depression in middle age remains unclear." (PMID 33863350, 2021). "Therefore, this work suggests that future research on GABRG2 might help identify specific groups of depression who might benefit the most from intensive treatment targeting cognitive symptoms or neurocognitive rehabilitation." (PMID 34733184, 2021).
Anxiety (6 papers, 2016 to 2024). Intense feelings of nervousness, tension, or panic often arise in response to interpersonal stresses. "In addition to seizures, it will be interesting to evaluate other Dravet-associated phenotypes in ZNS-treated Gabrg2+/Q390X mice, such as anxiety, social abnormalities, and spatial memory." (PMID 38731820, 2024). "Nevertheless, the downregulation of Gabrg2 in excitatory neurons in the motor cortex may have significant clinical relevance in addition to altered motor control, such as mental health conditions where loss/absence of Gabrg2 has been associated with anxiety behaviuors in Gabrg2 knockout mice." (PMID 38476460, 2024).
epilepsy syndrome (6 papers, 2016 to 2023). A syndrome that has a characteristic cluster of clinical features and/or lectroencephalographic (EEG) findings that reflect underlying epileptic activity. "Mutations in GABRG2 have been associated with epilepsy syndromes with varying severities." (PMID 36275690, 2022). "Furthermore, GABRG2(R82Q) and GABRG2(K328M) mutations that are mapped in the (+)γ subunit interface mutations were associated with mild epilepsy syndromes and were found to disrupt GABAA receptor function differentially." (PMID 27622563, 2016). "The structure/function correlation and variant phenotype of additional GABRG2 variants will undoubtedly nurture further studies on the precise role of γ2 subunits in GABAergic channelopathies and provide new insights into targeted therapy for epileptic syndromes." (PMID 36979350, 2023). "This suggests that there are GABRG2 epilepsy syndromes associated with GABRG2 variants that may have the same receptor targets (α1, β2,3 or γ2 subunits or α1β3γ2 receptors) and nonGABRG2 epilepsy syndromes that have different nonGABRG2 targets (α1 or β2,3 subunits or α1β2,3 receptors)." (PMID 34095830, 2021). "Among the common GABR genes with widespread distribution in the CNS and association with inherited epilepsy syndromes are GABRA1, GABRB2 and GABRG2." (PMID 34095830, 2021). "In this study, children with CHD4 mutations presented as CAE, BECTS, and EFS+, similar as several previously reported genes associated with idiopathic epilepsy, such as GABRG2, SCN9A, and GRIN2A,45, 46 suggesting these epileptic syndromes potentially have similar etiologies." (PMID 34109749, 2021).
febrile seizures (6 papers, 2011 to 2021). "Mutations in GABRG2 are associated with febrile seizures (FS) and various genetic epilepsy syndromes, which suggests a broad range of phenotypical spectrum associated with GABRG2 variants." (PMID 33391346, 2020).